USP2 (ubiquitin specific peptidase 2)
Diseases named in the same sentence as USP2 in open-access papers (continued):
Sharing a sentence is not in itself a finding about the gene and the disease.
lung carcinoma (3 papers, 2021 to 2023). "Despite current advances in USP2-related cancer research, the exact significance of the USP2-associated regulatory network of signal pathways in lung cancer cells is limited." (PMID 36567903, 2022). "USP2 significantly inhibited lung cancer by interacting with ARID2 and reducing ARID2 protein degradation via ubiquitination." (PMID 36567903, 2022). "Through mRNA and protein level detection, we discovered that majority of lung cancer cell lines had suppressed USP2, except for H1299." (PMID 36567903, 2022). "Our study suggested the complexity of the USP2-related ubiquitination regulatory network in carcinogenesis, which will enlighten future research on USP2's function in lung cancer." (PMID 36567903, 2022). "Firstly, immunoprecipitation-Mass Spectrometry (IP-MS), Co-immunoprecipitation (Co-IP), combined with immunofluorescent colocalization method, was conducted for USP2 protein interaction analysis in lung cancer cell lines." (PMID 36567903, 2022). "In this study, we first demonstrated that USP2 inhibited the malignancy of lung cancer by reducing ARID2 protein degradation via ubiquitination." (PMID 36567903, 2022). "Functional experiments suggested USP2 inhibited lung cancer cell invasion and migration by reducing ARID2 protein degradation." (PMID 36567903, 2022). "Comprehensive research of USP2 in lung cancer will be warranted to the full picture of its roles in lung cancer pathogenesis and progression." (PMID 36567903, 2022). "In summary, in this study, through lung cancer cell models and clinical sample analysis, we demonstrated for the first time that decreased USP2 expression pattern was a feature in lung cancer cells." (PMID 36567903, 2022). "In this study, we discovered that the expression of USP2 was significantly suppressed in lung cancer cell models and clinical tumor tissues, in comparison to NT." (PMID 36567903, 2022). "The study is aimed at providing novel insight into the roles of USP2 in future lung cancer research." (PMID 36567903, 2022). "USP2 exhibited inhibitory effects on lung cancer cell malignancy via ARID2 de-ubiquitination and protein degradation inhibition." (PMID 36567903, 2022). "Further functional studies including CHX chase assay, transwell assay, and wound healing assay were subsequently applied to evaluate the impact of USP2 modulation on lung cancer cells." (PMID 36567903, 2022). "In lung cancer cells, USP2 is distributed to the early endosome, and removes the polyubiquitin chain from internalized EGFR in early endosomes." (PMID 33530560, 2021). "Therefore, we aimed to further investigate the regulatory roles of USP2 in lung cancer in this study." (PMID 36567903, 2022). "Our study provided novel insight that USP2 might suppress lung cancer by reducing ARID2 protein degradation via ubiquitination." (PMID 36567903, 2022). "USP2 suppression was characteristic in lung cancer cell line models and lung cancer samples." (PMID 36567903, 2022). "Therefore, in this study, we evaluated the impact of USP2 and its molecular regulatory mechanisms in lung cancer pathogenesis and progression with lung cancer cell models and clinical samples." (PMID 36567903, 2022). "The results indicated that in both A549 and H1299 cells, ARID2 protein can be detected in anti-USP2 antibody precipitated protein samples, and vice versa, suggesting endogenously USP2-ARID2 protein-protein interaction (PPI) in lung cancer cells." (PMID 36567903, 2022). "However, the exact role of USP2 has not been well clarified in lung cancer pathogenesis and progression." (PMID 36567903, 2022).
osteosarcoma (3 papers, 2016 to 2025). A usually aggressive malignant bone-forming mesenchymal neoplasm, predominantly affecting adolescents and young adults. "Additionally, USP2, recruited by VCP, enhances the stability of fatty acid synthase (FASN) by removing K48−linked ubiquitin chains, a process whose inhibition reverses pro-tumorigenic effects in osteosarcoma cells." (PMID 40370434, 2025). "In addition, acute silencing of USP2 in human osteosarcoma U2-OS cells does not lead to an obvious alteration of the free-running period measured by bioluminescence." (PMID 26756164, 2016).
type 2 diabetes (3 papers, 2020 to 2026). "In hepatocytes, a short isoform of USP2, USP2b, aggravates type 2 diabetes and metabolic dysfunction-associated steatotic liver disease." (PMID 42072324, 2026). "Knockdown of Usp2 expression in the human myeloid cell line HL-60 is reported to alter the expression of genes involved in the progression of chronic inflammation and type 2 diabetes in adipose tissues, including aP2, PAI-1, and MCP-1." (PMID 33383715, 2020).
Anxiety (2 papers, 2021). Intense feelings of nervousness, tension, or panic often arise in response to interpersonal stresses. "In conclusion, our data indicate that Usp2 plays a role not only in the circadian system, but also in controlling various other behaviors such as anxiety-like phenotypes, motor coordination and working memory." (PMID 33621249, 2021). "More specifically, we have uncovered alterations of anxiety-like behavior, learning and memory, and motor coordination in mice with a deletion in the Usp2 gene." (PMID 33621249, 2021). "To test this, we subjected Usp2 KO and WT mice to a battery of tests, to assay various behaviors such as daily wheel running behavior, motor coordination, anxiety-like behavior, sensorimotor gating and memory." (PMID 33621249, 2021). "USP2 also maintains neural activity in the brain, and is postulated to be involved in special memory retrieval, motor coordination, short-term recognition, sensorimotor gating, and anxiety-like behavior." (PMID 33530560, 2021). "Thus, the EPM data indicates a reduced anxiety-like phenotype in the Usp2 KO mice." (PMID 33621249, 2021). "Further, mice lacking USP2 showed impaired motor coordination and equilibrium, a decrease in anxiety-like behavior, a deficit in working memory and in sensorimotor gating." (PMID 33621249, 2021). "Accordingly, we found a decrease in anxiety-like behavior in mice lacking Usp2, both in the EPM and the NSF tests." (PMID 33621249, 2021). "Thus, the observed phenotype of an increased latency to feed reflects mainly on a decrease in the anxiety-like behavior in mice lacking the Usp2 gene, consistent with the trend observed in the EPM test results." (PMID 33621249, 2021). "Further, based on high Usp2 expression in the hippocampus and cortex, we tested the mice for anxiety-like behavior and memory, and noticed a reduction in anxiety-like phenotypes and deficits in the working memory of Usp2 KO mice, but not in their spatial memory." (PMID 33621249, 2021).
clear cell renal cell carcinoma (2 papers, 2023 to 2025). "Likewise, ubiquitin-specific peptidase 2 (USP2) downregulates the NF-κB pathway, inhibiting EMT in clear cell renal cell carcinoma metastasis." (PMID 39901876, 2025).
gastric cancer (2 papers, 2023 to 2025). A primary or metastatic malignant neoplasm involving the stomach. "It has been reported that E2F4 binds directly with USP2 (ubiquitin specific peptidase 2) in gastric cancer cells, while USP2 could bind with SKP2 and USP2-stabilized SKP2 did not destabilize its substrate P21." (PMID 38980592, 2025).
major depression (2 papers, 2011 to 2018). "For example, the ubiquitous protein, UBC, was abnormally expressed in schizophrenia samples and interacted with the maker genes of schizophrenia (i.e. TSC2, SCNN1A and USP2), bipolar disorder (i.e. MUSK), and major depression (i.e. MUSK and FLT3)." (PMID 22373040, 2011).
mantle cell lymphoma (2 papers, 2021 to 2024). Mantle cell lymphoma is a rare form of malignant non-Hodgkin lymphoma affecting B lymphocytes in the lymph nodes in a region called the ``mantle zone''. "In numerous cell types, it promotes cell-cycle progression from G1 to S. USP2 becomes active or overexpressed in several cancers, such as mantle cell lymphoma, a subtype of non-Hodgkin’s lymphoma." (PMID 39664521, 2024). "USP2 inhibition by ML364 induces an increase in cellular cyclin D1 degradation and causes cell cycle arrest in mantle cell lymphoma (MCL) cell line (Mino cell)." (PMID 34454635, 2021).
Obesity (2 papers, 2023 to 2024). Accumulation of substantial excess body fat. "Several USPs, including USP2, USP10, USP14, USP15, USP18, and USP22, have been associated with obesity and related metabolic disorders." (PMID 38322269, 2024). "Furthermore, 3,3’-diindolylmethane, derived from cruciferous vegetables, inhibits adipogenesis in preadipocytes by targeting USP2 activity, thereby inhibiting high-fat diet-induced obesity." (PMID 38322269, 2024). "Since USP2, 7, 15, 19, and 20 stimulate either adipogenesis or lipid synthesis, they are likely to cause obesity, while USP53 might be restorative for obesity." (PMID 36834633, 2023). "It has been suggested that USP53, in contrast to USP2, 7, 15, 19, and 20, may have beneficial effects on obesity." (PMID 36834633, 2023). "A study indicates that USP2A and USP2 can alter insulin sensitivity, and USP2A blocks obesity-induced insulin resistance through adipocyte-dependent mechanisms." (PMID 38322269, 2024). "Several studies have utilized chemical blockers to assess the roles of USP in metabolic disorders; e.g., GSK2643953A for USP20 in obesity, ML323 and SJB-043 for USP1 in β-cell damage, ML364 for USP2 in hypothalamic function, and HBX41108 for USP7 in diabetic foot ulcers." (PMID 36834633, 2023).
ovarian carcinoma (2 papers, 2016 to 2018). A malignant neoplasm originating from the surface ovarian epithelium. "In contrast, lower level of USP2 was observed in ovarian cancer cells." (PMID 27780924, 2016).
acute myeloid leukemia (1 paper, 2021). Acute myeloid leukemia (AML) is a group of neoplasms arising from precursor cells committed to the myeloid cell-line differentiation. "USP2 is identified as a fusion partner of MLL (also known as KMT2A) in infant acute myeloid leukemia by using a whole transcriptome sequencing analysis." (PMID 34454635, 2021).
Ataxia (1 paper, 2023). Ataxia refers to impaired coordination of voluntary muscle movement. "Downregulated transcripts were found for the ATM interactome component Usp2, many non-coding RNAs, ataxia genes Itpr1, Grid2, immediate early genes and immunity factors." (PMID 37830614, 2023). "USP2-null mice show impaired motor coordination and balance, so its deficiency in an ATM-null cerebellum might contribute to ataxia pathogenesis." (PMID 37830614, 2023).
breast tumor (1 paper, 2019). "To examine if USP2 has a potential to be used as a diagnostic biomarker, we analyzed USP2 expression in 223 cases of breast tumor specimens." (PMID 30918246, 2019). "The histological analysis uncovered that USP2 expression is upregulated in breast tumors resected from patients with lymph node metastasis." (PMID 30918246, 2019). "To interrogate the potential clinical relevance of USP2 in cancer progression, we conducted immunohistochemistry staining of USP2 expression in 223 cases of breast tumor tissues." (PMID 30918246, 2019). "Our bioinformatics analysis of The Cancer Genome Atlas (TCGA) dataset by cBioPortal revealed that the USP2 gene is upregulated in around 20% of basal-like breast tumors." (PMID 30918246, 2019). "We also noticed that the percentage of breast tumor cases with high USP2 expression is increased in advanced pT status and tumor stages although the relationship is insignificant." (PMID 30918246, 2019). "Moreover, USP2 expression in breast tumors is positively correlated with the stage of lymph node metastasis (pN stage)." (PMID 30918246, 2019). "Additionally, we showed that USP2 expression is positively correlated with Twist and Bmi1 expression in breast tumor specimens." (PMID 30918246, 2019). "Furthermore, the histological analyses uncover that USP2 protein upregulation is correlated with lymph node metastasis of breast tumor." (PMID 30918246, 2019).
Cognitive impairment (1 paper, 2024). Abnormal cognition is characterized by deficits in thinking, reasoning, or remembering. "There was a significant decrease in Usp2 expression within the brain post 20 Gy, which could contribute to cognitive impairment." (PMID 38891920, 2024).
colitis (1 paper, 2023). Inflammation of the colon. "Other recent work has suggested that ubiquitin-specific protease 2 (USP2), which is upregulated in intestinal myeloid cells during IBD and mouse models of colitis, increases the expression of collagen and alpha smooth muscle actin (αSMA), leading to further ECM remodeling and tissue stiffening." (PMID 37492225, 2023).
embryonal carcinoma (1 paper, 2016). A non-seminomatous malignant germ cell tumor characterized by the presence of large germ cells with abundant cytoplasm resembling epithelial cells, geographic necrosis, high mitotic activity, and pseudoglandular and pseudopapillary structures formation.
esophageal squamous cell carcinoma (1 paper, 2025). Esophageal squamous cell carcinoma (ESCC) is a type of esophageal carcinoma (EC) that can affect any part of the esophagus, but is usually located in the upper or middle third. "In esophageal squamous cell carcinoma, hypoxia inhibits ferritinophagy-mediated ferroptosis through the USP2 (ubiquitin specific peptidase 2)-NCOA4 (nuclear receptor coactivator 4) axis." (PMID 39935430, 2025).
Hyperglycemia (1 paper, 2023). An increased concentration of glucose in the blood. "Given that HSD1 converts circulating inactive cortisone to active cortisol, hepatic USP2 causes hyperglycemia by activating glucocorticoid signaling." (PMID 36834633, 2023). "Conversely, hypothalamic USP2 alleviates hyperglycemia, indicating anti-diabetic roles." (PMID 36834633, 2023). "USP22 in pancreatic β-cells, USP2 in adipose tissue macrophages, USP9X, 20, and 33 in myocytes, USP4, 7, 10, and 18 in hepatocytes, and USP2 in hypothalamus improve hyperglycemia, whereas USP19 in adipocytes, USP21 in myocytes, and USP2, 14, and 20 in hepatocytes promote hyperglycemia." (PMID 36834633, 2023).
Hypoglycemia (1 paper, 2021). A decreased concentration of glucose in the blood. "Conversely, hypoglycemia, adiponectin, and PGC-1α, all of which are highly linked to cellular energy metabolism, control USP2 expression." (PMID 33530560, 2021). "Because the brain primarily utilizes glucose as its energy substrate, USP2 may therefore play a neuroprotective role against hypoglycemia." (PMID 33530560, 2021).
Insulin resistance (1 paper, 2023). Increased resistance towards insulin, that is, diminished effectiveness of insulin in reducing blood glucose levels. "Moreover, macrophage USP2 represses adipose tissue inflammation and subsequent insulin resistance." (PMID 36834633, 2023).
juvenile arthritis (1 paper, 2020). "Previously, MIF was reported in association with susceptibility to juvenile arthritis, GSTT2 with S-phenylmercapturic acid levels in smokers, and USP2 suggestively with urate levels." (PMID 33137956, 2020).
liver cancer (1 paper, 2022). An epithelial or non-epithelial malignant neoplasm that arises from the liver. "USP22, USP14, USP10, USP13, USP7, USP2, and USP8, liver cancer-related DUBs, have also been reported to have related small molecule inhibitors, but the research and development are not mature enough." (PMID 35875077, 2022).
lung adenocarcinoma (1 paper, 2022). A carcinoma that arises from the lung and is characterized by the presence of malignant glandular epithelial cells. "Moreover, TCGA gene expression profiling datasets of lung squamous cell carcinoma (LSCC) and lung adenocarcinoma tumor samples were utilized to validate the pattern of USP2/ARID2 mRNA expression." (PMID 36567903, 2022).
lymph node metastasis (1 paper, 2019). "Furthermore, the histological analyses reveal a positive correlation between USP2 upregulation and lymph node metastasis." (PMID 30918246, 2019).
lymphoma (1 paper, 2016). A malignant (clonal) proliferation of B- lymphocytes or T- lymphocytes which involves the lymph nodes, bone marrow and/or extranodal sites. "However stronger USP2 staining was observed in lymphoma cells in the plaques than in the tumors." (PMID 27351221, 2016).
male infertility (1 paper, 2026). The inability of the male to effect fertilization of an ovum after a specified period of unprotected intercourse. "Meanwhile, in testicular macrophages, USP2 protects the mitochondrial respiration of sperm and consequently contributes to maintaining the quality of frozen sperm for use in the treatment of male infertility." (PMID 42072324, 2026).
medulloblastoma (1 paper, 2025). A malignant, invasive embryonal neoplasm arising from the cerebellum. "Elevated USP2 expression is also associated with poor prognosis in medulloblastoma." (PMID 40370434, 2025).
melanoma (1 paper, 2023). A malignant, usually aggressive tumor composed of atypical, neoplastic melanocytes. "Moreover, co-immunoprecipitation analysis of human melanoma A375 cell extracts indicate that endogenous VPRBP and USP2 proteins interact in vivo." (PMID 37024504, 2023).
metabolic syndrome (1 paper, 2020). A cluster of metabolic risk factors for CARDIOVASCULAR DISEASES and TYPE 2 DIABETES MELLITUS. "DNA microarray analysis was used to investigate the kidney expression of four genes (Cyp24a1, Plin2, Calb1 and Usp2), which are reported to be involved in metabolic syndrome and LSRD." (PMID 33383715, 2020).
mycosis fungoides (1 paper, 2016). Classical mycosis fungoides is the most common type of mycosis fungoides (MF), a form of cutaneous T-cell lymphoma, and is characterized by slow progression from patches to more infiltrated plaques and eventually to tumors. "USP2 is expressed in neoplastic cells in early, plaque-stage mycosis fungoides (MF) and is downregulated in advanced tumor stages." (PMID 27351221, 2016).
myeloid sarcoma (1 paper, 2025). A tumor mass composed of myeloblasts or immature myeloid cells. "The PDX 49 represents a unique case of myeloid sarcoma within this cohort, and retained STR, morphology and fusions (CBL – USP2, SMG5–CTSS, and KPNA1–CBFA2T2) identical to those of the original tumor." (PMID 40801203, 2025).
nephrolithiasis (1 paper, 2016). The presence of a calculus in the pelvis of the kidney; this is most often composed of mineral salts and proteins. "This percentage may increase by screening nephrolithiasis patients for mutations in USP2 or in clock genes controlling its expression such as ARNTL (BMAL1) and CLOCK and their binding sites in the promoter of USP2." (PMID 26756164, 2016).
non-alcoholic fatty liver disease (1 paper, 2023). "USP4, 10, and 18 in hepatocytes ameliorates non-alcoholic fatty liver disease (NAFLD), while hepatic USP2, 11, 14, 19, and 20 exacerbate it." (PMID 36834633, 2023).
osteoporosis (1 paper, 2016). A condition of reduced bone mass, with decreased cortical thickness and a decrease in the number and size of the trabeculae of cancellous bone (but normal chemical composition), resulting in increased fracture incidence. "Furthermore, Usp2-KO mice handle long-term reduction of dietary Ca2+ intake without loss of body weight, lowering of plasma Ca2+ or compensatory osteoporosis." (PMID 26756164, 2016).